PANX1 (pannexin 1)
Diseases named in the same sentence as PANX1 in open-access papers (continued):
Sharing a sentence is not in itself a finding about the gene and the disease.
melanoma (continued). "Our results showed that Panx1 global deletion did not reduce the strong BRAF/Pten‐driven melanoma progression but increased the tumor infiltration of effector immune T‐cell populations." (PMID 38327091, 2024). "Moreover, mRNA expression of the S100a1 melanoma marker had a 5.1‐fold increase (P < 0.05) in tumors of BPC‐Panx1−/− compared to the skin, indicating that the development of primary tumors occurred independently of Panx1 expression." (PMID 38327091, 2024). "Our results showed that regardless of the Panx1 genotype, melanocytic pigmented lesions arose from the skin and quickly grew to form cutaneous melanomas as early as 3 weeks after topical application of 4‐HT." (PMID 38327091, 2024). "Although the absence of Panx1 downregulates β-catenin expression in melanoma cells, β-catenin expression in non-loaded Panx1 knockout (Panx1−/−) osteocyte-enriched cells is unaffected." (PMID 34392490, 2021). "We previously reported that long-term exposure to PANX1 channel blockers, namely Carbenoxolone (CBX) and Probenecid (PBN), reduces the growth rate of melanoma cells evident after 3 days in culture, a phenotype that is also observed in cells with depleted PANX1 protein." (PMID 33647315, 2021). "PANX1 staining was found primarily in melanoma tumor cores and stromal regions, with no labeling found in necrotic areas." (PMID 30654593, 2019). "This duality in Panx1 function could be influenced by tumor stage, molecular context, or interactions with specific proteins, such as AHNAK in rhabdomyosarcoma or β-catenin in melanoma." (PMID 40978734, 2025). "Considering the broad PANX1 expression and different cell types present in the tumor microenvironment (TME), no studies have specifically addressed whether PANX1 modulates the recruitment of immune cells in the melanoma TME." (PMID 38327091, 2024). "Nevertheless, it remains to be tested whether the absence of PANX1 in a specific subtype of the immune cell in the tumor could be exploited to counterbalance the immunosuppressive or evasive mechanisms of melanoma." (PMID 38327091, 2024). "Of note, overexpression of PANX1 in A375-MA2 cells does not substantially increase the abundance of PANX1 at the cell surface, suggestive of mechanisms by which melanoma cells may retain PANX1 intracellularly and prevent its translocation to the cell surface." (PMID 30654593, 2019). "Furthermore, since PANX1 expression seems independent of genomic alterations of melanoma and is present at all stages of the disease, a larger patient population may benefit from PANX1 targeted therapy." (PMID 38327091, 2024). "Therefore, we concluded that Panx1 deletion does not control the early spread of melanoma." (PMID 38327091, 2024). "As NB and melanoma are both neural crest-derived tumors that may have a shared genetic basis 58, future studies will investigate the role of EMT and the Wnt-β-catenin pathway, in addition to that of ATP release and P2 receptors, in the PANX1-mediated regulation of NB malignant properties." (PMID 37056395, 2023). "Of note, our previous in vitro and ex vivo work targeting PANX1 in melanoma employed murine B16‐F0, B16‐F1, B16‐F10, and human BRAF(V600E)‐mutant melanoma cell lines (A375‐P and A375‐M2) that do not entirely share the same genomic alterations of the BPC model." (PMID 38327091, 2024). "We have previously shown that mouse melanocytes have low Panx1 expression while the aggressiveness of isogenic melanoma cell lines (B16-FO, F10 and BL6) is directly correlated to their Panx1 levels, with no detectable Panx2 or Panx3 expression." (PMID 27229305, 2016).
epilepsy (26 papers, 2013 to 2026). A brain disorder characterized by episodes of abnormally increased neuronal discharge resulting in transient episodes of sensory or motor neurological dysfunction, or psychic dysfunction. "Up-regulation of pannexin-1 expression has been demonstrated to exert an essential influence in multiple brain injury diseases such as epilepsy, sepsis-associated encephalopathy, and subarachnoid hemorrhage." (PMID 38803679, 2024). "Aberrant Panx1 activity has been implicated in several conditions affecting the central nervous system (CNS), including ischemia, epilepsy, and Alzheimer’s disease." (PMID 36429074, 2022). "Dysregulation of Panx1 activity was implicated in several neurodegenerative diseases including Parkinson’s and Alzheimer’s diseases, ischemia, epilepsy, and in migraine and neuropathic pain." (PMID 36291086, 2022). "Herein, we assess the changes in behavioral and electrophysiological markers of excitability associated with Panx1 via three distinct models of epilepsy." (PMID 33053775, 2020). "What is known of Panx1 in epilepsy is that the protein becomes upregulated in association with seizures in both rodent and human tissue." (PMID 33053775, 2020). "Panx1 and Panx2 channel overexpression has also been linked to epilepsy." (PMID 36140338, 2022). "Furthermore, Panx1 channel activation is implicated in seizure activity in humans and animal models of epilepsy." (PMID 34068881, 2021). "Increasing experimental and clinical evidence indicates that Panx1 overexpression may be associated with epilepsy." (PMID 28036289, 2017). "The PANX1 gene modulates neural activity, both enhancing and inhibiting it under pathological conditions, such as ischemia, trauma, inflammation, and epilepsy, and is also essential for vascular function." (PMID 40282202, 2025). "In epilepsy animal models, both Panx1 channel blockers and Panx1 gene knockout can effectively suppress seizures." (PMID 40217413, 2025). "Of note, the deletion of pannexin-1 provided potent anticonvulsive effects during kainic acid (KA)-induced SE in mice and resected brain tissue from epilepsy patients." (PMID 40601217, 2025). "Pannexin1 (Panx1) is expressed in both neurons and glia where it forms ATP-permeable channels that are activated under pathological conditions such as epilepsy, migraine, inflammation, and ischemia." (PMID 36291086, 2022). "Studies have shown that PANX1 is involved in the occurrence and development of cell proliferation, cell differentiation, inflammation, cerebral ischemia, epilepsy, and tumors." (PMID 36675706, 2022). "The roles of Panx1 channels in neuronal excitability and experimental epilepsy models are controversial and incompletely understood." (PMID 35585187, 2022). "The channel protein Panx-1 is involved in some pathologies, such as epilepsy, ischemic stroke, cancer and Parkinson’s disease, as well as in neuropathic pain." (PMID 35563213, 2022). "Panx1 is recognized as a pro-convulsant channel after behavioral and electrophysiological markers of excitability are ameliorated in distinct models of epilepsy once Panx1 is inhibited pharmacologically or by global deletion in mice." (PMID 35585187, 2022). "Of note, the same authors showed potent anticonvulsive effects when blocking pannexin-1 during KA-induced seizures in mice, suggesting drugs targeting ATP release mechanisms as novel treatment strategies for seizures and epilepsy." (PMID 35216493, 2022). "Studies evaluating Cx43 and Panx1 inhibition by different compounds have yielded promising results in neurodegenerative diseases, stroke, pain and epilepsy." (PMID 36140338, 2022). "Enhanced activity and overexpression of Pannexin 1 (Panx1) channels contribute to neuronal pathologies such as epilepsy and Alzheimer’s disease (AD)." (PMID 36429074, 2022). "Recently, the involvement of Panx-1 in some pathologies, such as epilepsy, ischemic stroke, cancer, and Parkinson’s disease has demonstrated." (PMID 35563213, 2022).
epilepsy (continued). "The combination of function and position of Panx1 channels makes them a noteworthy contributor to the hyperexcitable dynamics in epilepsy." (PMID 33053775, 2020). "Three distinct models of epilepsy presented here corroborate a significant pro-epileptic effect of the Panx1 channel." (PMID 33053775, 2020). "Genetic or pharmacological targeting of pannexin-1 channels have anticonvulsant effects in epilepsy models." (PMID 33202963, 2020). "Pannexin-1 expression seems raised in animal seizure models and in resected human epileptic brain tissue, suggesting relevance to epilepsy." (PMID 33202963, 2020). "We interrogate various brain regions through different models of epilepsy, focusing on analyzing local field potential recordings in mice with Panx1 channels blocked or genetically deleted." (PMID 33053775, 2020). "Significance: These results suggest that Panx1 plays a pivotal role in maintaining neuronal hyperexcitability in epilepsy models and that genetic or pharmacological targeting of Panx1 has anti-convulsant effects." (PMID 33053775, 2020). "Panx-1 channels are exciting new targets as global panx-1 inhibition has anticonvulsive effects in animal models of epilepsy." (PMID 33324329, 2020). "One of the main candidates for ATP release are Panx1 HCs and Cx43 HCs, whose activity and expression has been mostly founded in pathological conditions, including epilepsy." (PMID 30542266, 2018). "Correlations between Panx1 protein levels and different clinical variables (age at surgery, epilepsy duration, seizure frequency) of all the FCD patients were assessed." (PMID 28036289, 2017). "Increasing evidence suggests that the large-pore ion channels, pannexin 1 (Panx1) and 2 (Panx2), are involved in epilepsy and brain development." (PMID 28036289, 2017). "Therefore, we concluded that Panx1 might be associated with cell-induced epilepsy in FCD." (PMID 28036289, 2017). "The expression of Panx1 channels is increased in a mouse model of kainic acid-induced epilepsy, but whether Panx1 mainly activates or inhibits epilepsy remains controversial." (PMID 40217413, 2025). "The differences reported here between the modes of activation between Panx1 orthologs are likely to have important implications to translational studies into disorders such as epilepsy and chronic pain, where Panx1 channel activation has been shown to have significant impact." (PMID 38100403, 2023). "PBN could be of interest in the pharmacology of epilepsy since Panx1 hemichannels are involved in the pathophysiology of epilepsy." (PMID 37371611, 2023). "Moreover, the overexpression of Panx1 has been associated with neuronal hyperactivity and death, and aberrant activity of Panx1 has been observed in several brain disorders, including ischemia, epilepsy, and Alzheimer’s disease." (PMID 36429074, 2022). "Some studies have demonstrated that Panx1 plays important role in regulating epilepsy." (PMID 34658792, 2021). "Others have reported that the absence of Panx1 reduces seizure activity in an animal model of epilepsy, indicating that Panx1 may be intrinsically involved in the maintenance of excitation in physiological ranges." (PMID 33796018, 2021). "Furthermore, panx-1 in conjunction with P2X7R potentiates seizure activity in an animal model of epilepsy as well as in brain slices of patients with TLE." (PMID 33324329, 2020). "By using a chronic epilepsy model, we show here that hyperexcitability observed in hippocampal astrocytes is driven by purinergic signaling, likely ATP, and requires the participation of Panx1 HCs and subsequent P2Y1R activation." (PMID 30542266, 2018). "Moreover, areas with high Panx1 expression are regions that become hyperexcitable in experimental models of epilepsy." (PMID 29551976, 2018). "Our IHC study further displayed that Panx1 was specifically distributed in the abnormal cells, suggesting that Panx1 might participate in the processes of these cells induced epilepsy." (PMID 28036289, 2017).
epilepsy (continued). "Importantly, the protein levels of Panx1 positively correlated with the frequency of seizures, which suggested a potential role of Panx1 in FCD induced epilepsy." (PMID 28036289, 2017). "Recent studies in the CNS have suggested the Panx1 channels is important for certain physiological functions (e.g., synaptic plasticity, learning) and its abnormalities account for several pathological processes (e.g., ischemia, tumorigenesis, epilepsy)." (PMID 28036289, 2017). "Furthermore, a pattern of sex-specific differences in functional Panx1 impairment requires ongoing investigation as it may be critical to the clinical relevance of Panx1 as an effective therapeutic target for epilepsy." (PMID 33053775, 2020). "Moreover, Panx1-KO mice treated with kainate exhibited less severe seizures and lower extracellular concentrations of ATP compared to kainate-treated WT-mice, strongly suggesting an important role for Panx1 HCs in mediating ATP release in epilepsy." (PMID 30542266, 2018). "Considering the association of epilepsy and various developmental disorders with FCD, understanding the expression pattern and cellular localization of Panx1 and Panx2 in FCD could provide constructive insights into their potential roles in the epileptogenesis and pathogenesis associated with FCD." (PMID 28036289, 2017). "Panx1 channels also interact with other proteins, such as the purinergic receptor P2X7 and possibly inflammasome components involved in the innate immune response and associated secondary cell death, thus responsible for amplification of the primary lesion in CNS trauma, stroke and epilepsy." (PMID 23675350, 2013). "However, over the past decade, Panx1 channels have been identified as an effective mechanism for ATP release in various inflammatory conditions that affect the CNS, including in models of TBI, cerebral ischemia, and epilepsy." (PMID 34068881, 2021). "Thus, Panx1 HCs and P2Y1Rs expressed in astrocytes could represent a novel therapeutic target for seizure control and epilepsy treatment." (PMID 30542266, 2018).
ischemia (26 papers, 2012 to 2025). A hypoperfusion of the BLOOD through an organ or tissue caused by a PATHOLOGIC CONSTRICTION or obstruction of its BLOOD VESSELS, or an absence of BLOOD CIRCULATION. "Panx1 channel activation is broadly associated with pathological processes including cancer, ischemia, platelet activation, seizure, immune cell migration, and HIV viral replication." (PMID 34068881, 2021). "To test whether the resistance of RGCs in Panx1−/− mice to hypertension-induced ischemia is linked to Panx1 channel activity, we compared RGC loss in zygotic knockouts, conditional neuronal knockouts and in WT retinas treated with 2.0 mM probenecid." (PMID 29643381, 2018). "This study demonstrates that neurons could be protected from ischemia-associated damage by blocking NMDA/P2X receptors as well as Panx-1 hemichannels." (PMID 24672487, 2014). "Therefore, we hypothesized that a pathological cascade leading to ischemia-induced RGC loss is triggered by the opening of Panx1 channels." (PMID 22384122, 2012). "Phosphorylation at Tyr308 is a key step for PANX1 activation in the NMDAR/Src/PANX1 signalosomes that eventually leads to the neuronal cell death during ischemia or stroke." (PMID 38168229, 2024). "Similar to HCs, the persistent opening of Panx1 channels has been proposed to be harmful to cells, contributing to cell death in episodes of ischemia or facilitating viral infection." (PMID 36555574, 2022). "On the other hand, the administration of probenecid, a well-known Panx1 inhibitor, resulted in reduction of neuronal death and inflammasome activation in a rat model of ischemia." (PMID 34068881, 2021). "There is evidence that an increase in the level of expression of Cx43 and Panx1, which occurs during ischemia, enhances the ATP release into the extracellular space and thus ATP acts as an “alarm signal”." (PMID 34360859, 2021). "The effect of EC deletion of Panx1 has also recently been shown in ischemia, with deletion of Panx1 inducing a significant decrease in leukocytes after occlusion of the middle cerebral artery, lessening the overall impact of the ischemic response." (PMID 29874791, 2018). "In ischemia damage models, deletion of Panx1 in RGCs provides a protective response, including attenuation of neurotoxic Ca2+ uptake." (PMID 27126275, 2016). "The combination of high permeability to ATP, ions, and other molecules, and activation by diverse injury-induced DAMPs, makes Panx1-expressing neurons highly sensitive to mechanical and ischemia injuries." (PMID 24575045, 2014). "It has been proposed that Panx1 channels are involved in pathways activated upon a strong stimulus, such as inflammation, ischemia, or myocardial infarction." (PMID 23390418, 2013). "In isolated brain neurons, the opening of the Panx1 channel was shown to permeate the plasma membrane in response to 15 minutes of ischemia, thus allowing molecules to cross the plasma membrane." (PMID 22384122, 2012). "Panx1 ion and metabolite-permeable channels are known to open in several pathological circumstances, including elevated extracellular potassium, ischemia and elevated amyloid beta peptide exposure, a pathogenic feature of Alzheimer’s disease (AD)." (PMID 22458943, 2012). "In support of the key role of mechanosensory Panx1 signaling in the retina, recent reports showed its pivotal role in both acute ischemia-induced and glaucomatous degeneration, where its activity strongly correlated with the induction of the inflammasome and production of IL-1β." (PMID 37998361, 2023). "Panx1 isoforms oligomerize to form hexameric plasma membrane channels that are closed in physiological conditions but open in pathological ones (e.g., ischemia, hypoxia, mechanical stimulation) to release ATP and other small signaling molecules and increase membrane permeability." (PMID 35325354, 2022).
ischemia (continued). "They concluded that the opening of Panx1 channels may be the major contributor to the dysregulation of ionic fluxes that leads to neuronal necrosis after ischemia." (PMID 34068881, 2021). "Neuronal Panx1 channels, first demonstrated by Thompson and his colleagues, have been shown to activate early on after oxygen glucose deprivation in an in vitro model of ischemia." (PMID 34068881, 2021). "In addition, Panx1 HC activity is also increased in neurons under ischemia." (PMID 41036176, 2025). "Next, we investigated whether Panx1 ablation influences intracellular [Ca2+]i dynamics in ischemia." (PMID 22384122, 2012). "Relevantly, Panx1 cleavage evoked by caspase 11 was crucial for facilitating the ATP release and posterior activation of the NLRP3 inflammasome during ischemia/reperfusion-induced by AKI." (PMID 36555574, 2022). "During ischemia, NMDAR activates SFKs, which in turn phosphorylates site Y308 in the C-terminal of Panx1 to activate Panx1 and induce secondary ischemic currents." (PMID 29534733, 2018). "Thus, opening of Panx-1 hemichannels and activation of P2 receptors play a major role in the pathogenesis of ischemia and blocking or knocking down these hemichannels/receptors could provide additional therapeutic interventions to reduce damage and to improve recovery in response to ischemic events." (PMID 24672487, 2014). "Furthermore, disturbing the NMDAR-Src-PANX1 complex has been found to be neuroprotective after ischemia or stroke, suggesting that the NMDAR–PANX1 axis might be involved in thrombo-inflammation." (PMID 33114406, 2020). "Secondly, in the rat hippocampus slice, NMDAR–Src–Panx1 is found to co-localize in a metabotropic signaling complex and NMDAR couples SFK to Panx1 during ischemia in response to glutamate and glycine but not Ca2+ influx through NMDAR." (PMID 32070042, 2020).